IL17A (interleukin 17A)
Diseases named in the same sentence as IL17A in open-access papers (continued):
Sharing a sentence is not in itself a finding about the gene and the disease.
tumor (continued). "Additional chemokines and growth factors, such as TGF‐α, CCL4, CCL20, IL‐17A, IL‐2RB, and FGF‐23, further underscore the multifaceted interplay between inflammation and tumor biology through pathways ranging from proliferation and angiogenesis to immune cell recruitment." (PMID 41458898, 2025). "This study suggested that tumor cells rather than immune cells are the primary cells that produce IL-17A in OS." (PMID 40486048, 2025). "Similarly, wound healing assays demonstrated that IL17A and IL26 individually promoted the migratory capacity of tumor cells, while combined treatment elicited the highest migration rate." (PMID 40452847, 2025). "Mice lacking IL17A—either genetically or through pharmacological depletion—exhibited prolonged survival and smaller tumours, compared to vaccinated controls." (PMID 40831074, 2025). "Targeting the TH17 cell axis, particularly through the inhibition of IL-17A, has emerged as a promising strategy to mitigate irAEs without compromising the efficacy of ICIs in tumor control." (PMID 40535343, 2025). "Meanwhile, our mIHC experiments also verified that infiltration of effector CD8+ T cells declined remarkably during tumor progression in BOT models, whereas statistically significant accumulation of IL17A+ γδ T cells and Treg cells was detected in the TIME of SC models." (PMID 40899264, 2025). "NK cell depletion in untreated models further demonstrated NK cells’ critical function in controlling tumour growth when IL17A was absent." (PMID 40831074, 2025). "It is noteworthy that in KPC/IL17A−/− mice, NK cells depletion significantly restarted tumour growth but did not affect tumours in KPC/IL17A+/+ mice." (PMID 40831074, 2025). "There is some experimental evidence highlighting the potential of HT to impede tumor progression by modulating the expression levels of IFN-γ, PD-1, IL-17A, and MHC I. Notably, IL-2, IL-10, and IL-17A have been implicated in inhibiting immune escape mechanisms." (PMID 40313970, 2025). "IL-17A promotes the proliferation of cancer cells not by directly influencing tumor cell growth but by indirectly facilitating tumor expansion through the modulation of the immune microenvironment." (PMID 40558272, 2025). "Further research found that L. reuteri could increase acetate levels, and acetate then reduced the production of IL-17A in hepatic type 3 innate lymphoid cells (ILC3), thus exerting an anti-tumor effect." (PMID 40185720, 2025). "At the molecular level, the expression of Il4, Il17a, and Il33, but not that of Tslp, Ccl20 or Ccl27a, was dramatically lower in the skin lesions of the IL-1R antibody-treated SSKO mice than in those of their IgG-treated SSKO littermates." (PMID 39939818, 2025). "Collectively, these findings emphasize the dominant regulatory role of IL-8 in modulating IL-17A activity during tumor invasion and highlight the absence of a direct relationship involving IL-33 in this context." (PMID 40725273, 2025). "In this study, tumor immunological profiling following bacterial depletion revealed an increase in anti-tumor immune lymphocytic cells (CD3+CD4+IFNγ+, CD3+CD8+IFNγ+, and CD3+IFNγ+), while a decrease in pro-tumorigenic IL17a (IL17a + CD3 +) and IL10(IL10 + CD4 + CD3 +)." (PMID 39044834, 2024). "There is no direct effect of IL-17A on endothelial cell proliferation, but it can make fibroblasts and tumor cells produce proangiogenic factors." (PMID 38515019, 2024). "Furthermore, cytokines such as IL-6, IL-21, IL-17A, and tumor necrosis factor-α (TNF-α) induce tumor-supportive microenvironment, while interferon-γ (IFN-γ) exerts tumor-suppressive response." (PMID 38741166, 2024). "In sarcomatoid-tumor FOV, differential expression by individual cell phenotype revealed tumor cells having significant downregulation of IL17A compared to nonsarcomatoid-tumor FOV (FDR < 0.001) along with 7 other genes." (PMID 39639369, 2024).
tumor (continued). "IL‐17A and TNF synergistically induced the Th17‐promoting cytokines IL‐6 and IL‐1β as well as the Th17‐attracting chemokine CCL20 in mesothelial cells, indicating a reciprocal crosstalk that potentiates the tumor‐promoting role of Th17 cells in OC." (PMID 38566518, 2024). "In addition, IL-17A can promote the secretion of IL-1β, IL-18, and other inflammatory factors and immune antigens, recruit CD8 + T cells to infiltrate the tumor and inhibit the progression of CRC." (PMID 39906741, 2024). "Th17 cells are a veritable cytokine factory, producing a range of cytokines and chemokines, including IL-17A, IL-17F, IL-21, IL-22, TNF-α, and CCL20, which modulate the behavior of fibroblasts, endothelial cells, epithelial cells, macrophages, and tumor cells, thereby sculpting the TME." (PMID 39906741, 2024). "Consistently, in this study, we showed that an aggressive TCF3high phenotype was strongly correlated with the progression of malignancy, migration, and proliferation of tumor cells and rescued the activation of the NK-κB and VEGF signaling pathways after IL-17A induction." (PMID 39205642, 2024). "Th17 cells produce IL-17A, which facilitates cancer cell migration, invasion, and stemness through the STAT3/NF-κB/Notch1 signaling pathway, while also recruiting MDSC cells in the TNBC tumor microenvironment, further enhancing tumor progression." (PMID 39867914, 2024). "The IL‐17 family of cytokines consists of six groups: IL‐17A, IL‐17B, IL‐17C, IL‐17D, IL‐17E and IL17‐F, which are involved in the development of autoimmunity, inflammation, tumours, host defences against bacterial and fungal infections, and mucosal host defence mechanisms." (PMID 38363001, 2024). "Moreover, IL-17A+ CD8+ T cells secrete IL-17A, which, in conjunction with TNF signaling, can induce iCAFs and promote tumor progression." (PMID 38982491, 2024). "Previous studies showed that IL-17A promotes BRAC invasion, which may indicate a pro-tumor effect of inflammation." (PMID 39235230, 2024). "Although there was no statistical difference observed between the anti-IL-17A group and anti-IL-17A + M. globosa group, the tumor volume in the anti-IL17A + M. globosa group was reduced compared with the M. globosa group." (PMID 39235230, 2024). "Additionally, IL-17A recruits more CD8+ T cells to the tumor microenvironment, thereby demonstrating an anti-tumor immune response." (PMID 39408824, 2024). "IL-17A/IL-17RA induced CCL2 and attracts macrophages into the tumor environment." (PMID 39906741, 2024). "Moreover, interleukin-17 (IL-17A) can stimulate angiogenesis through promoting FAO and thus a potential therapy for angiogenic vascular disorders that lead to tumor progression." (PMID 38841622, 2024). "Indeed, elevated levels of IL-17A-producing cells such as Th17, IL-17A, and its receptor were observed in NSCLC specimens and were correlated with tumor progression and poor prognoses." (PMID 37444399, 2023). "A significant negative correlation was found between serum IL-17A concentrations and the tumor estrogen receptor expression." (PMID 37427128, 2023). "In liver cancer cell lines, IL-17A may stimulate angiogenesis induced by CXC chemokines, independently of VEGF signaling, to promote tumor progression in mice." (PMID 37686343, 2023). "In the cell culture system, IL-17A addition profoundly inhibited ICAM-I expression on endothelial cells and suppressed the transmigration of CTLs, particularly the stem-like subset, across the tumor vascular endothelium." (PMID 37605139, 2023). "ENTPD1, IL17A, and P2RX7 were downregulated, while HSP90AA1, PIK3CA, and NT5E were upregulated, indicating that ENTPD1, IL17A, and P2RX7 might negatively affect tumor development and result in better outcome." (PMID 37587188, 2023). "A statistically significant up-regulation of the cytokine IL-17A and all of the adhesion molecules in NR-T group, compared to the other ones, was observed, regardless of the primary tumor type." (PMID 37483633, 2023).
tumor (continued). "We first isolated bone marrow–derived myeloid cells (BMDMs) from WT C57BL/6J mice and cultured them in tumor cell conditioned medium from 7940b cells with or without IL-17A." (PMID 36239683, 2023). "IL-17A stimulation suppressed the extravasation across tumor vascular endothelium and self-renewal of stem-like, not the terminally exhausted CTLs." (PMID 37605139, 2023). "IL-1β and IL-17A are known to negatively regulate Regnase-1 and we found significant upregulation of IL-1β but did not detect IL-17A expression in the tumor sites." (PMID 37814340, 2023). "Furthermore, treatment with extracellular vesicles significantly enhanced the expression levels of crucial molecules in the IL-17A pathway, IL-17A, TRAF6 and c-FOS in tumor tissue and suppressed immune responses of CD8+ cells in vivo." (PMID 37373022, 2023). "It cannot be ruled out that the differentiation of IL-17A-producing γδ T cells occurs within the tumor microenvironment, but this possibility requires further experimental confirmation." (PMID 37631976, 2023). "Tumor-specific upregulation of cytokines produced by Th17 CD4+ cells, such as IL-17A and IL-22, has been observed in human CRC, and studies in mouse models of spontaneous intestinal tumorigenesis have demonstrated the importance of these cytokines in tumor progression." (PMID 38096329, 2023). "Our results indicate that lack of IL-17A suppresses the development of H. pylori-induced GC, supporting its role as an important tumor-promoting factor in this model." (PMID 36125689, 2023). "After MNU and H. pylori treatment, immunoreactivity for IL-17A was present in inflammatory as well as surface mucous cells and gastric glands, but not tumor cells." (PMID 36125689, 2023). "After MNU and H. pylori treatment, immunoreactivity for IL-17A was detected in the cytoplasm of inflammatory cells as well as surface mucous epitheliums and gastric glands, but not tumor cells." (PMID 36125689, 2023). "Transforming growth factor β(TGF-β), IL-23, and IL-1β can promote the differentiation of Th17 cells to produce IL-17A/F, which regulates cancer cell proliferation, migration, epithelial mesenchymal transition (EMT)through NF-κB pathway to promote tumor development and metastasis." (PMID 37978543, 2023). "The exact mechanism by which IL-17A engagement affects the tumour immune microenvironment to influence tumour progression has not been identified." (PMID 37211606, 2023). "IL-17A expression in tumor tissue and peritumoral stroma is significantly higher than in healthy breast tissue but does not correlate with IL-17A serum values either before surgery or during adjuvant treatment." (PMID 37427128, 2023). "Therefore, neutrophil frequency and the phenotype of conventional T cells was investigated in tumor-bearing KB1P mice treated with anti–PD-1, anti–TIM-3, or anti-ICOS, as a systemic readout of increased IL-17A by γδ T cells." (PMID 36480166, 2023). "IL-17A also promote tumor angiogenesis independent of the conventional vascular endothelial growth factor (VEGF)." (PMID 37605139, 2023). "In addition, IL-17A can promote the secretion of inflammatory factors such as IL-1β、IL-18 and immune antigens, and recruit CD8 + T cells to infiltrate tumours." (PMID 37211606, 2023). "Together, these results indicate that Th1 cells, but not IL‐17a‐producing cells (including Th17 cells), are involved in the anti‐tumor response generated by EVax treatment in our tumor model." (PMID 35861366, 2022). "To further confirm the important role of IL-17A in the BTNL2 blockage, we purified murine IL-17A-Fc recombinant proteins, and found that treatment with recombinant IL-17A-Fc also abolished the anti-tumour effect of BTNL2 blockade." (PMID 35017553, 2022). "In addition, numerous studies have found that the characteristic chemokines of Type 17 T cells, such as IL-17A, IL-17F, GM-CSF, and CCL20, recruit T cells, B cells, neutral granulocytes, and macrophages into tumor tissue in various tumor models." (PMID 35459193, 2022).
tumor (continued). "IL‐17A+FOXP3+ Tregs are a subpopulation of suppressive Tregs, which could be promoted by TGF‐β during tumor progression." (PMID 35474948, 2022). "To better understand the role of these CD4+ T cell subsets in tumor protection induced by EVax immunization, we examined the impact of neutralizing IFN‐γ (the major cytokine player of Th1 cells) and IL‐17a (the major cytokine player of Th17 cells) in EVax‐treated mice." (PMID 35861366, 2022). "Studies on the impact of IL-17A in the TME have yielded both pro- and anti-tumor functions." (PMID 35924165, 2022). "Further results of ELISA showed that the expression IL-17A and TNF-α were upregulated by YYFZBJS treatment, which suggested that YYFZBJS blocked tumor progression in CRC murine model possibly via inhibiting the accumulation of Treg cells in immune organs, and in tumor microenvironment." (PMID 36212483, 2022). "Identification of immune cells that secrete IL-17A and express MDR1 in the tumor microenvironment may help clarify the controversial role that IL-17A plays in solid neoplasms." (PMID 36297616, 2022). "Interestingly, we found their receptors, IL17RA/IL17RC for IL17A/IL17F, IL10RB/IL22RA1 for IL22, and IL20RA/IL10RB for IL26, were upregulated in tumor cell than in normal epithelial cells." (PMID 35999201, 2022). "Although cytokine expressions of TNF-α, IL-6, IL-17A, and TGF-β1 are sensitive phenotyping biomarkers in radiation-induced cardiopulmonary toxicities, they are not specific in differentiation of inflammation/infection versus tumor recurrence." (PMID 36591530, 2022). "The unpaired data revealed that the IL17A expression was similar in normal and tumor tissues (p = 0.38), but paired analysis showed significantly decreased IL17A expression in tumor tissues compared with that in paired normal samples (p = 0.0055)." (PMID 35902909, 2022). "Second, IL-17A could increase the expression of CTSK in PC cells and in tumor tissues of mice, and promote EMT marker expression through CTSK in PC cells." (PMID 36138018, 2022). "In addition to IFNγ, Ling and colleagues also reported elevated IL-17A production by MAIT cells in both the periphery and tumours of patients with CRC." (PMID 33808058, 2021). "In summary, we confirmed the significant effect of anti-IL-17A combined with anti-PD-1 therapy in the MSS CRC murine model and observed the effect of antitumor immune response induced by this combination therapy in the tumor microenvironment." (PMID 33462141, 2021). "As for anti-tumor responses, whereas cytokine responses were mostly absent in nerve-intact mice, IL-17A, IL-6, and IL-10A were found elevated in sympathectomized tumor-bearing mice." (PMID 33691777, 2021). "Antibody depletion of IL-17A in combination with MEK inhibition and PD-L1 blockade produced a durable reduction in lung tumor growth, metastasis, and prevented the development of tumor resistance." (PMID 33972557, 2021). "While blocking IL-17A and/or ERK5 significantly improved the anti-tumor activity of anti-VEGF, in an unknown mechanistic manner." (PMID 34456740, 2021). "Therefore, we verified the effect of combined anti-IL-17A antibodies and anti-PD-1 antibodies in CT26 and MC38 tumor-bearing mice." (PMID 33462141, 2021). "Moreover, we found cells co-expressing IL-17A and CD4 both in the stroma and tumor regions, which accounted for 22% and 17% of all IL-17A+ cells, respectively, and for 2% and 6% of all CD4+ cells, respectively." (PMID 34944746, 2021). "Others have described modulation of cytokine production of IL-1α, IL-1β, IL-2, IL-4, IL-6, IL-8, IL-10, IL-17A, TNF-α, and IFN-γ on tumor cells treated with conventional PDT, but their increase or decrease seems to highly depend on the cell line and PDT protocol used." (PMID 32326519, 2020). "In addition, the cytokines IL-1α, IL-1β, IL-6, IL-17A, and TNF-α promote tumor initiation, progression, angiogenesis, and metastasis in many human malignancies, including CRC, and our findings are consistent with previous studies." (PMID 33488574, 2020).
tumor (continued). "Given that IL-17A-positive cells were mainly derived from the CD4+ cell population, Th17 cells may be the primary source of IL-17A in tumor tissues." (PMID 32503584, 2020). "Having shown that AdIL-17A transduction in 4T1 cells induces both immune activation and MDSC-mediated immune suppression, we hypothesized that IL-17A-activated CD4 and CD8 T cells would exert anti-tumor effects if MDSCs were depleted." (PMID 32770025, 2020). "Since IFNγ and IL-17A do not directly kill tumor cells (not shown), these data suggest that the increase in cytotoxic factors is responsible for tumor cell killing." (PMID 33042110, 2020). "Tumor-infiltrating T, B, and NK cell levels and plasma concentrations of Th1 (IL-2, IFN-γ, and TNF-α), Th2 (IL-4, IL-5, IL-6, and IL-10), Th9 (IL-9), and Th17 (IL-17A, IL-17F, IL-21, and IL-22) cytokines were evaluated." (PMID 32802733, 2020). "Indeed, we found an increased frequency of IL-17A and IL-22 producing CD4+ T cells in the tumor compared with adjacent normal tissue in patients with CRC." (PMID 32451418, 2020). "Furthermore, TCRγδCD8− T cells secreting both IL-17A+ and TNF+ are significantly increased in tumor tissue, compared to unaffected tissue." (PMID 32185408, 2020). "Overall, our findings support a model wherein Th17 cells inhibit the expression of CXCR3 on CD8+ T cells in blood circulation by secreting IL-17A, which activates STAT3 signaling and downregulates CD8+ T cell infiltration in tumor tissues; these effects can be attenuated via Stattic." (PMID 32503584, 2020). "In culture medium from iTh17 cells harvested from aged OVX mice treated with calcitriol (not significant) or PRI-2191 (p<0.05) the level of IL-17A was lower as compared to control tumor-bearing mice." (PMID 32257539, 2020). "A study has shown that targeting IL-17A in ER-negative breast cancer inhibits the expression of PD-L1 in tumor cells." (PMID 33102239, 2020). "The role of IL-17A on tumor progression has not yet been clearly determined; therefore, studying the effect of IL-17A on the infiltration of immune effector cells in patients with CRC is warranted." (PMID 32503584, 2020). "Besides the detrimental effect of IL-17A, the pro-inflammatory cytokine TNF also plays a role in intestinal polyp formation in the APCΔ468 mouse model and TNF blockade diminishes tumor development." (PMID 32185408, 2020). "Immunofluorescence further found that (61.6 ± 7.5) % of IL-17a protein was expressed by CD66b + neutrophils in the tumor stroma which was significantly higher than that in the nontumoral tissues (15.4 ± 5.8)% (P < 0.001)." (PMID 30616627, 2019). "We successfully demonstrated IL-17A induced MHC class I expression and promotes tumor antigenicity in PTC, and may be related to PD-1/PD-L1 pathway." (PMID 31159823, 2019). "In contrast to IL-17A, deletion of IL-17C did not affect Kras-induced intrinsic inflammation and tumor cell proliferation within the observation period of 12 weeks." (PMID 31316109, 2019). "Targeting Th17 or IL17A pathways as a treatment for cancer has not yet been reported in clinical trials; however, two recent reports suggest their important role in anti-tumor activity." (PMID 31921642, 2019). "In one study, IL-17A promoted the invasiveness of EAC cells, whereas in another study, it played a protective role in human ESCC by enhancing the cytotoxic effects of NK cells, killing tumor cells, and activating CD1a+ DCs in tumors." (PMID 31771653, 2019). "In this context, IL-17A has been found to promote tumor cell growth and proliferation, angiogenesis via production of vascular endothelial growth factor (VEGF) by tumor cells, as well as invasion and metastasis via production of matrix metalloproteinase-9 by tumor cells and other cell types." (PMID 31616428, 2019).